CD47 (CD47 molecule)
Diseases named in the same sentence as CD47 in open-access papers (continued):
Sharing a sentence is not in itself a finding about the gene and the disease.
tumor (continued). "Recent Phase 1 clinical trials attempting to convert protumorigenic macrophages to anti-tumorigenic macrophages by blocking the CD47-SIRPα axis, for example, and making macrophages less immunosuppressive and more phagocytic of tumor cells themselves, have shown promise." (PMID 40004162, 2025). "CD47 is a membrane protein widely expressed in various tumor cells." (PMID 40385528, 2025). "In this system, the tumor cells treated with oAd-CD47 promoted the migration of CAR-Ms." (PMID 40814015, 2025). "Mechanistically, the binding between CD47 on tumor cells and SIRPα on DCs and macrophages mitigates phagocytosis activities of DCs and macrophages and further dampen their antigen presentation activity to result in tumor immune evasion." (PMID 40908470, 2025). "Moreover, by cancer-directed CD47 blockade, we abolished CD47-related on-target off-tumor toxicities." (PMID 40402266, 2025). "In this study, we hypothesized that overexpression of phosphoSTAT3Y705 and CD47 in OS are therapeutic targets and that blocking these two pathways will synergize and potentiate anti-tumor response." (PMID 40529368, 2025). "CD47, a natural immune checkpoint, may play a key role in tumor immune evasion, and the combination of CD47 antibodies with rapamycin has been shown to enhance antitumor effects in mice." (PMID 40787068, 2025). "CD47 expression leads to reduced phagocytosis by APCs during inflammatory conditions, and finding ways to mitigate this is a valuable strategy to support the development of anti-tumor immune responses prompted by cancer immunotherapies, such as oncolytic NDV." (PMID 41322194, 2025). "In addition, combo therapy with CD47 blockade significantly inhibited cell proliferation, and increased necrosis and apoptosis of the tumour tissues." (PMID 40240911, 2025). "In research targeting lung metastasis of OS, MPIRx (a biomimetic nanodrug composed of a sonosensitizer and a CD47 inhibitor) is capable of directing macrophages towards tumor cells, fostering M1 polarization, and enhancing the phagocytic activity of macrophages towards OS cells." (PMID 40534850, 2025). "CD47 is a widely expressed glycoprotein that transmits a “don’t eat me” signal through interaction with signal regulatory protein α (SIRPα) on macrophages, a mechanism exploited by tumor cells to evade immune surveillance." (PMID 40963633, 2025). "Consequently, targeting STAT3 inhibition or employing anti-CD47 monoclonal antibodies can enhance TAM-mediated phagocytosis of tumor cells, thereby mitigating EGFR-TKI resistance." (PMID 40003951, 2025). "After incubating EC cells with different targeting molecules, flow cytometry results showed that the affinity between the CD47 antibody and tumor cells was significantly higher than the other two targeting molecules (GnRHa and folate) (the content and figure in the supplement)." (PMID 40385528, 2025). "Although we confirmed that CD47 expressed on the tumor cell surface can promote Th2 cell infiltration in the TME, the underlying mechanism of CD47 promoting the Th2 cell‐mediated suppression of anti‐tumor immunity is not defined." (PMID 40548645, 2025). "Additionally, immune checkpoint pathways such as CD47/SIRPα inhibit phagocytosis by delivering a “don’t eat me” signal from tumor cells to macrophages." (PMID 41462587, 2025). "Collectively, CD47 suppresses both innate and adaptive immunity to promote tumor immune escape." (PMID 41514569, 2025). "CD47 serves as a "don't eat me" signal, enabling tumor cells to escape phagocytosis by macrophages." (PMID 41003851, 2025). "The tumor-intrinsic CD47 signaling pathway is another pivotal mechanism in immune escape." (PMID 40655153, 2025). "In addition, to enhance the efficacy of CAR-NK cells, we also incorporated CV1, a CD47–SIRPα axis inhibitor, to evaluate the anti-tumor effect of this combination." (PMID 40487639, 2025).
tumor (continued). "However, severe hemolytic reactions and drug resistance pose challenges to the anti-tumor efficacy of CD47-targeting therapies." (PMID 38398223, 2024). "However, it is important to note that there was also an increase in pro-tumor CD163+ M2 macrophages in the anti-CD47 treatment group." (PMID 38532108, 2024). "In addition, anti-CD47 antibody-mediated phagocytosis can be enhanced by combination with tumor-targeting antibodies." (PMID 38464520, 2024). "In addition, an “imbalanced” design with a decreased binding affinity to CD47 and increased binding affinity to tumor cell surface proteins can retain tumor-specific phagocytic stimulation activity while retaining host cells to limit toxicity." (PMID 38464520, 2024). "Therefore, one of the major challenges in the development of CD47 antibody-based anticancer drugs is to maximize the killing of tumor cells while ensuring the protection of red blood cells." (PMID 38429732, 2024). "We observed a significant increase in the number of CD69− and CD69+CD103−/+ populations within both polyclonal CD8+ and SIINFEKL+ TIL, suggesting that CD47 × PD‐L1 BisAb treatment promotes a wide‐spread influx of T cells including both tumor‐reactive and polyclonal T cell populations." (PMID 39584189, 2024). "Moreover, targeting the CD47-SIRPα axis was significantly effective in inhibiting tumor progression in an ovarian cancer model, which was involved in macrophage-mediated phagocytosis in vitro." (PMID 39169402, 2024). "Further analysis has revealed that administration of CD47 antibodies combined with olaparib may improve tumor control." (PMID 38787372, 2024). "Furthermore, we also confirmed CD47 overexpression in all tumor cell lines (U251vIII: 56.5%, U251: 51.4%, U87: 53.5%, BS153: 80.6% and Raji: 58.4%), compared to NSCs used as a normal brain cell control (right plot)." (PMID 39521782, 2024). "Additionally, immune adjuvants, including anti‐CD47 antibodies (aCD47) and CaCO3 nanoparticles, are directly released into the resected tumor bed." (PMID 39467056, 2024). "CD47 expression varied between samples and tumor compartment." (PMID 39310770, 2024). "Importantly, recent studies indicate that PARPi combined with anti-CD47 antibody showed significant anti-tumor effects in HR-proficient animal models." (PMID 38317230, 2024). "The results of the flow cytometry analysis showed that compared to IMM01 (SIRPα Fc fusion protein), all CD38/CD47 BsAbs had a greater ability to bind to CD38+ tumor cell lines in a concentration-dependent manner, and the binding ability of 35G5 and 12C10 was greater than that of the other BsAbs." (PMID 38983860, 2024). "However, CD47 is also expressed on numerous normal tissues and cells, and develop a suicide gene or affinity optimization anti-CD47 CAR-T would reduce on-target/off-tumor effects." (PMID 38783333, 2024). "Subsequently, in a subcutaneous transplantation tumor model using Foxp1-deficient LLC cells treated with anti-CD47 Ab, it was observed that Foxp1 deletion partially prevented the increase in the CTLA4 level induced by anti-CD47 Ab treatment." (PMID 38398223, 2024). "We hypothesize that simultaneously enhancing the csCRT-mediated “eat me” signal and inhibiting the CD47-mediated “don’t eat me” signal will effectively boost the phagocytic activity of TAMs and result in significantly impaired ES tumor growth and metastasis." (PMID 38992659, 2024). "This over-activation may lead to the cyclization of CD47 N-terminal pyroglutamate on the surface of tumor cells, and thus enhances the binding capacity to SIRPα." (PMID 38429732, 2024). "Blocking CD24-Siglec interactions may enhance anti-tumor immune responses, similar to strategies targeting CD47 or PD-L1/PD-1." (PMID 39040441, 2024). "Many tumor cells upregulate CD47 expression to escape the immune system." (PMID 39594765, 2024). "Furthermore, the addition of CD47 nanobody to the bacterial PTT regimen showed maximal anti‐tumor efficacy and prolonged survival." (PMID 38888519, 2024).
tumor (continued). "The use of anti-CD47 antibodies has shown promising potential in promoting tumor cell elimination through various mechanisms, including the enhancement of phagocytosis by macrophages and the augmentation of non-phagocytic killing by neutrophils and natural killer (NK) cells." (PMID 38429732, 2024). "Targeting of SIRPα, the binding partner of CD47, may therefore offer a safer alternative approach with which to modulate myeloid-driven anti-tumor immunity, as it is almost exclusively expressed by the myeloid compartment." (PMID 38577107, 2024). "Based on our results, we hypothesized that combining HDAC6i with anti-CD47 could result in tumor regression and modulation of the macrophage phenotype in vivo." (PMID 38414061, 2024). "In addition, blocking CD47 leads to phagocytic uptake of tumor cells by antigen-presenting cells, facilitating subsequent antigen presentation to T cells." (PMID 38638433, 2024). "In vitro anti-tumor effect of blocking CD47 was examined by phagocytosis assays." (PMID 39335665, 2024). "In addition, PD-L1 and CD47 on the surface of colorectal CSCs also led to early escape of tumor cells from immune surveillance during tumor development." (PMID 38254219, 2024). "Based on the previously reported role of Vtn-C1qbp signaling in tumor immune response, we further investigated whether Vtn knockdown and anti-CD47 antibody treatment have a synergistic anti-tumor effect." (PMID 38773982, 2024). "Only the combination of NextA and anti-CD47 led to a significant decrease in tumor growth." (PMID 38414061, 2024). "Additionally, as the phagocytic effect of macrophages on tumor cells was enhanced after blocking CD47, we explored and found that the knockdown of Tug1 in tumor cells dramatically enhanced the phagocytosis of co‐cultivated macrophages." (PMID 38981064, 2024). "However, the tumor growth delay was more pronounced when both anti-CD47 Ab and anti-CTLA4 Ab were administered together compared to the single-agent treatment groups." (PMID 38398223, 2024). "In addition to targeting CD47, it has been found that SIRPα–blocking antibodies combined with CSF-1R inhibitors can stimulate the activation of anti-tumor macrophages." (PMID 39169402, 2024). "Additionally, it was observed that the depletion of CD4+ T cells in mice while targeting CD47 led to a slight elevation in the tumor volume compared to targeting CD47 alone." (PMID 38398223, 2024). "However, tumor cells eventually upregulate surface “don’t eat me” receptors, the most well-characterized of which is CD47." (PMID 39194679, 2024). "However, tumor cells have hijacked this mechanism by overexpressing CD47, allowing them to evade immune surveillance and leading to adverse clinical outcomes." (PMID 38783333, 2024). "Nevertheless, the function of CD47 in tumor angiogenesis is not yet well understood." (PMID 38398223, 2024). "Furthermore, the combination of Vtn knockdown and anti-CD47 antibody effectively enhanced phagocytosis and infiltration of macrophages, resulting in a reduction of tumor growth in vivo." (PMID 38773982, 2024). "Consequently, the investigation of triple-negative breast cancer (TNBC) elucidates the significant contribution of CD47 in the development and advancement of tumor load." (PMID 38397971, 2024). "Nonetheless, the net reduction of CD47 and PD-L1 on dying/dead and viable tumor cells induced by DSF/Cu may contribute to an enhanced ICD." (PMID 38678042, 2024). "It was investigated whether anti-CD47 Ab regulated intra-tumor vasculature and functioned through increased CD4+ cell infiltration." (PMID 38398223, 2024). "Another study demonstrates how the EGFR pathway cooperates with CD47 to promote tumor progression." (PMID 39194679, 2024). "Previous studies have demonstrated that simultaneously high CD47 and positive PD-L1 expression on tumor cells could synergistically promote tumor development, and that dual-blockade could achieve better anti-tumor effects than single blockade of CD47 or PD-L1." (PMID 38317230, 2024).
tumor (continued). "Next, we compared CD47 abundance between different tumor grades (G1–3)." (PMID 38493445, 2024). "Another correlative study of RRMM patients from the CoMMpass trial showed higher CD47 expression along with low CD38 expression correlated with worse overall survival and that dual inhibition of CD38 and CD47 had anti-tumor efficacy over single target inhibition." (PMID 38322418, 2024). "However, CD47 is ubiquitously expressed in healthy as well as diseased tissue, from tumor cells to erythrocytes, bladder, prostate, fallopian tubes, mediumly in bronchus tissue, salivary glands, and sex organs." (PMID 38577107, 2024). "However, it is worth noting that the administration of anti-CD47 treatment led to an escalation in microvessel density within the tumor, potentially fostering an immunosuppressive microenvironment and constraining the effectiveness of CD47 blockade." (PMID 38532108, 2024). "Indeed, when myeloid cells encountered a CD47-rich environment, impaired phagocytosis of tumor cell debris was observed." (PMID 38577107, 2024). "In this context, our analysis has not revealed any association between tumor grade and the expression of CD47." (PMID 38493445, 2024). "Moreover, CD47 ligation using an immobilized 47VHH1H4 leads to apoptosis of U937 tumor cells characterized by CD47 overexpression." (PMID 38247566, 2024). "In addition, a versatile nanoplatform has been created to enhance the infiltration of T lymphocytes, eliminate tumor cells, and regulate immune responses by targeting PD-L1 and CD47 signals in breast cancer." (PMID 39309874, 2024). "However, due to the upregulation of anti-phagocytic molecules such as CD47 on tumor cells, which makes it difficult to activate macrophage phagocytosis, Du and colleagues constructed a co-delivery nanocarrier aCD47-DMSN." (PMID 39334825, 2024). "Altogether, these results support our hypothesis that NextA and anti-CD47 can act in combination in vivo to decrease tumor growth and to modulate the phenotype of TAMs." (PMID 38414061, 2024). "Furthermore, studies using the CRISPR/Cas9 delivery system have reported tumor-specific CD47 inhibition and, additionally, the transformation of tumor cells into IL-12 production factories." (PMID 38543240, 2024). "Tumor cells hijack this pathway and overexpress CD47 to evade immune destruction." (PMID 38319147, 2024). "Here, SMC18 could effectively block PD-1/PD-L1 interaction and CD47/SIRPα interaction to achieve a synergic effect in inhibiting tumor growth." (PMID 38462636, 2024). "Moreover, a metastatic model is also worth examining to determine if there is potential to hinder tumor colonization by targeting CD47 and angiogenesis." (PMID 39335665, 2024). "Additionally, the combination of checkpoint blockade using CD47 nanobody can synergistically enhance the anti‐tumor effect of PTT mediated by biohybrid‐engineered bacteria." (PMID 38888519, 2024). "Moreover, both calreticulin released during ICD and CD47 blockade can accelerate phagocytosis of tumor cells by macrophages, promote antigen presentation, and eventually induce T lymphocyte-mediated antitumor immunity." (PMID 38560565, 2024). "We found that miR‐340 inhibited tumor growth and Cd47 expression significantly." (PMID 38981064, 2024). "We also discovered that the CD47-SIRPA mediated tumor cell evasion from macrophage phagocytosis." (PMID 39119581, 2024). "NILK-2401 is a fully human BsAb binding the CEACAM5 N-terminal domain on tumor cells by its lambda light chain arm with an affinity of ≈4 nM and CD47 with its kappa chain arm with an intendedly low affinity of ≈500 nM to enabling tumor-specific blockade of the CD47-SIRPα interaction." (PMID 38720892, 2024). "When inhibiting the activation of innate immunity, tumor antigen presentation and priming of the T cell response, CD47 may enable tumor cells to evade both innate and adaptive immune surveillance." (PMID 38612630, 2024).
tumor (continued). "From our results, we hypothesized that the combination of NextA and targeting the CD47/SIRPα axis would decrease SM1 tumor growth." (PMID 38414061, 2024). "The biological hybrid nanoparticles were synthesized by fusion of CD47-expressing tumor exosomes and tumor-targeting peptide cRGD (cyclic arginine-glycine-aspartic acid) modified liposomes (miR497/ TP-henPs), which were responsible for the delivery of miR497 and TP." (PMID 38832992, 2024). "Furthermore, CD47 overexpression by tumor cells serves as an important mechanism for constructing the immunosuppressive tumor microenvironment and, hence, providing an effective target for cancer immunotherapy." (PMID 38508139, 2024). "In breast cancer, Wnt signaling drives cell proliferation and metastasis and was recently shown to suppress the anti-tumor immune response, for example, through its major target, Myc, that activates expression of cell antigens (e.g., CD47), preventing tumor cell recognition by the immune cells." (PMID 38474826, 2024). "Based on a study, tumor cells overexpressed CD47 and PD-L1 (CD274) to evade immune cell clearance." (PMID 39256364, 2024). "Furthermore, the successful implementation of anti-angiogenic treatment has further augmented the anti-tumor efficacy of anti-CD47 therapy." (PMID 38532108, 2024). "However, tumor cells can evade the killing of macrophages with anti-tumor activity through high expression of CD47." (PMID 39065562, 2024). "Additionally, THBS1 modulates innate and adaptive immune cells through the CD47 signaling molecules, thereby restricting anti-tumor immunity." (PMID 39010084, 2024). "Moreover, clinical trials have demonstrated that a combination of CD47 mAbs and ICIs results in a reduced tumour burden and prolonged survival." (PMID 38468489, 2024). "In addition, the anti-CD47 antibody blocks CD47 on tumor cells, thus coating them with antibodies that can potentially enhance the antitumor immune response." (PMID 38414061, 2024). "CD47, an immune checkpoint protein highly expressed on tumor cells, interacts with SIRPα on macrophages and induces phosphorylation of SIRPα to transmit a "don't eat me" signal, enabling tumor cells to evade immune surveillance." (PMID 38462636, 2024). "Based on these findings, we hypothesized that pre-treatment with the agonistic RTX-IgG2 – which reduces the anti-phagocytic CD47 on the surface of target cells – could enhance the phagocytic efficacy of other tumor-targeting mAbs." (PMID 39712032, 2024). "Whereas H151 treatment could significantly reverse the tumor suppressive effect of engineered bacteria‐mediated PTT plus CD47 nanobody, which clearly demonstrates the critical role of the STING pathway in this combinational therapy regimen." (PMID 38888519, 2024). "Therefore, the inhibition of CD24 and CD47 has become a new strategy of anti-tumor immunotherapies and has prompted great research potential in recent years." (PMID 38787372, 2024). "Consequently, targeting the CD47/SIRPα axis holds significant promise for advancing tumor immunotherapy." (PMID 38275876, 2024). "Finally, we tested the anti-tumor effect of co-targeting CD47 and angiogenesis using a bispecific fusion protein, SIRPα-VEGFR1, which successfully inhibited tumor growth to a similar extent as a combination therapy." (PMID 39335665, 2024). "CD47 is a transmembrane protein with a well-described role as a “don’t eat me” signal due to its binding to signal regulatory protein a (SIRPa) on myeloid cells and high CD47 expression on tumor cells is thought to protect tumor cells from immune responses." (PMID 39281684, 2024). "Bispecific antibodies targeting CD47 and PD‐L1 (CD47 × PD‐L1 BisAb) demonstrate efficacy against a range of solid cancers, but the effect of combined innate and adaptive immune activation on protective tumor‐resident CD8+ T cells has yet to be fully elucidated." (PMID 39584189, 2024).